POT1 (protection of telomeres 1)
Diseases named in the same sentence as POT1 in open-access papers (continued):
Sharing a sentence is not in itself a finding about the gene and the disease.
gastric adenocarcinoma (1 paper, 2015). "A particularly relevant recent report specifically associated various POT1 variants with telomere length and radiosensitivity in colon and gastric adenocarcinoma." (PMID 26636039, 2015). "Taken together with the reported association of POT1 variants with radiosensitivity and colon and gastric adenocarcinoma, our results suggest that heavy ion radiation therapy may be particularly effective in treating these cancers." (PMID 26636039, 2015).
Hypertension (1 paper, 2019). The presence of chronic increased pressure in the systemic arterial system. "In another independent replication cohort consisting of 3,183 African American samples from Hypertension Genetic Epidemiology Network (HyperGEN) and the Genetic Epidemiology Network of Arteriopathy (GENOA), the top genes achieved P-values of 0.04 (ITGA7), 0.08 (SLCO2A1), and 0.02 (POT1)." (PMID 30863429, 2019).
Li-Fraumeni syndrome (1 paper, 2025). "A recent international publication suggested a surveillance protocol similar to that used in Li-Fraumeni Syndrome (LFS) could be offered to POT1 pathogenic variant carriers, particularly where there are LFS-like features." (PMID 40350252, 2025).
liver cancer (1 paper, 2020). An epithelial or non-epithelial malignant neoplasm that arises from the liver.
lymph node metastasis (1 paper, 2017).
mantle cell lymphoma (1 paper, 2020). Mantle cell lymphoma is a rare form of malignant non-Hodgkin lymphoma affecting B lymphocytes in the lymph nodes in a region called the ``mantle zone''. "Regarding somatic mutations, several POT1 variants have been detected in a mantle cell lymphoma cohort (5.4%, n = 3/56), and somatic POT1 mutations might also contribute to the formation of sporadic parathyroid tumors." (PMID 32987645, 2020).
monoclonal gammopathy of undetermined significance (1 paper, 2023). "An increase in expression of POT1, RAP1, TIN2, and ACD has been observed in MM cases than monoclonal gammopathy of undetermined significance (MGUS), predicting telomere role and as prognostic markers." (PMID 37131110, 2023).
Ovarian cyst (1 paper, 2022). The presence of one or more cysts of the ovary. "It is worth noting that no POT1 mutations were detected in the two individuals (II6 and III3) with pulmonary nodules and/or ovarian cysts." (PMID 36387164, 2022).
parathyroid adenoma (1 paper, 2014). "No mutations in genes recently proposed to be implicated in parathyroid adenoma tumorigenesis, such as CTTNB1, EZH2 and POT1, were identified, attesting to the rarity of these candidate genes' potential contributions." (PMID 25594030, 2014).
prostate carcinoma (1 paper, 2024). A carcinoma that arises from epithelial cells of the prostate gland. "A recent study reported higher prostate cancer among men with POT1 PV, but with a median age of onset of 67.5 years." (PMID 38839987, 2024). "The tested carrier in this family (II.5) presented an early onset prostate cancer and a STS, tumours not traditionally associated with POT1-TPD, but already reported in another POT1 related study." (PMID 38839987, 2024).
renal carcinoma (1 paper, 2024). A carcinoma arising from the epithelium of the renal parenchyma or the renal pelvis. "Shelterin expression predicted patient survival in 24 cancer types, with TERF1, TERF2, TINF2, and POT1 significantly expressed in testicular, AML, prostate, breast and renal cancers, respectively, and TPP1 in AML and skin cancer." (PMID 39578854, 2024).
thoracic aortic aneurysm (1 paper, 2018). An aneurysm formed in the wall of the proximal portion of the descending aorta proceeding from the arch of the aorta. "Moreover, POT1 was already established as a biomarker for thoracic aortic aneurysms and dissections 40,41." (PMID 30613281, 2018).
thymoma (1 paper, 2025). A neoplasm arising from the epithelial cells of the thymus. "The most frequently mutated genes within each subtype were as follows: PCLO (27%), POT1 (27%), and STAT3 (27%) in idiopathic PRCA; STAT3 (20%), DNMT3A (10%), and CUX1 (10%) in thymoma-associated PRCA; and STAT3 (54%) and TET2 (12%) in LGLL-associated PRCA." (PMID 40202536, 2025).
Tumor Syndrome (1 paper, 2024). "Thereafter, various cancers have been proposed as associated with germline POT1 variants in the context of the so-called POT1 Predisposition Tumor Syndrome (POT1–TPD)." (PMID 38254993, 2024).
viral infection (1 paper, 2021). "Further analysis demonstrated that the wider resistance spectrum by pot1 was comparable to that by an eIF4E1 and eIF4E2 double mutant, suggesting that pot1 lacks the function to support viral infection but can compete with eIF4E2 or inhibit its interaction with viruses." (PMID 34454519, 2021).
cancer (86 papers, 2010 to 2026). A tumor composed of atypical neoplastic, often pleomorphic cells that invade other tissues. "It is recognised that these recommendations will need to be reviewed and updated as we learn more about the spectrum of cancers and cancer risk in POT1-TPDS." (PMID 40350252, 2025). "This guidance was also supported by a more recent publication describing the cancers identified in three large families with POT1 LP variants, ascertained through clinical genetics on the basis of personal and family histories of cancer." (PMID 40350252, 2025). "Overall, current estimates of risk are likely to be overestimated due to ascertainment bias and more studies are needed to assess the role of POT1 in susceptibility to cancer." (PMID 40350252, 2025). "Provide lifetime cancer risk estimates for individuals with POT1 likely pathogenic/pathogenic (LP/P) variants, overall and for specific cancers." (PMID 40350252, 2025). "The UK Cancer Genetics Group (UKCGG), in collaboration with the National Disease Registration Service, is creating a national registry of individuals with inherited cancer predisposition that will include POT1 heterozygotes." (PMID 40350252, 2025). "Most of our current understanding about cancer phenotype and risk in POT1-TPDS has arisen from case reports where cases have been selected based on specific clinical characteristics and thus are likely to be subject to ascertainment bias." (PMID 40350252, 2025). "Current estimates of risk are likely to be overestimated, and more studies are needed to assess the role of POT1 in cancer susceptibility." (PMID 40350252, 2025). "Studies showed that pathogenic variants in the POT1 gene are associated with the alteration of the telomere length and a subsequent increased risk for cancer." (PMID 38254993, 2024). "Since more than 50 variants in POT1 were identified either as germline predisposition alleles, or somatic mutations in different cancers, evidence was collected to consider POT1 as a relevant gene in the tumorigenesis process." (PMID 38254993, 2024). "While the key role, and related risks, of the alterations in POT1 in melanoma are established, the correlation between germline POT1 variants and the susceptibility to other cancers partially lacks evidence, due also to the rarity of POT1–TPD." (PMID 38254993, 2024). "Some POT1 gene pathogenic variants (PV) lead to telomere elongation, genomic instability and higher risk of cancer." (PMID 38839987, 2024). "The dysregulation of TPP1/POT1 can lead to either aberrant telomere elongation or excessive shortening, both of which are implicated in cancer development." (PMID 39012375, 2024). "The broad range of POT1 gene variations that cause cancer in many tissues indicates the universal significance of these genes." (PMID 39239547, 2024). "Mutations in the human Protection of Telomeres 1 (POT1) gene are frequently detected in cancers with abnormally long telomeres, suggesting that the loss of POT1 function disrupts the regulation of telomere length homeostasis to promote telomere elongation." (PMID 37560909, 2023). "Cancer-associated POT1 mutations lead to reduced CST association with telomeres, and are epistatic with CST loss in increasing telomere fragility, suggesting POT1 and CST prevent fragility in the same pathway, but this requires further study." (PMID 36833275, 2023). "In this study, we utilized these ‘separation-of-functions’ POT1 mouse models to better understand how cancer mutations in hPOT1 promote telomere elongation." (PMID 37560909, 2023). "POT1 mutations have been detected in various cancers including chronic lymphocytic leukemia, glioma, melanoma, angiosarcoma, and colorectal cancer." (PMID 37332576, 2023).
cancer (continued). "A telomere length test was conducted on 13 surviving POT1 mutation carriers from five families, and it was found that gene POT1 mutations prevent telomere shortening and increase the incidence of benign and malignant tumors." (PMID 37588048, 2023). "Expression of several cancer-associated POT1 variants leads to telomere elongation and sometimes to increased telomere fragility." (PMID 35323213, 2022). "The knock-in Pot1aR117C/+ mouse model constitutes a useful tool to understand human cancers initiated by POT1 mutation." (PMID 35727838, 2022). "POT1 mutations in cancer patients that support telomere length extensions through impaired recruitment of telomerase to the telomere have been characterized." (PMID 35774233, 2022). "Cancer-associated POT1 alterations include diverse heterozygous loss-of-function variants believed to promote tumorigenesis in telomerase-expressing cells via telomere elongation, thereby extending the proliferative capacity and preventing senescence of cells." (PMID 35456397, 2022). "The Pot1a+/R117C mouse model constitutes a useful tool to understand human cancers initiated by POT1 mutations." (PMID 35727838, 2022). "Based on his strong history of cancer and discovery of the POT1 variant, the patient was referred to a clinical geneticist by his oncologist for counseling and further evaluation." (PMID 35456397, 2022). "Across the spectrum of germline POT1 variants associated with cancer predisposition, p.Ile49Metfs*7 is the earliest frameshift mutation ever reported." (PMID 35456397, 2022). "Generating mouse models carrying LFL-associated POT1 mutations will be instrumental to understand the role of POT1 in the pathobiology of various cancers and to search for new therapeutic opportunities." (PMID 35727838, 2022). "The overall findings, however, suggest that this germline early truncating POT1 variant likely explains this individual’s remarkable personal and family history of cancer." (PMID 35456397, 2022). "Our findings solidate this finding and assign MM as a novel cancer included in the spectrum of POT1‐associated malignancies." (PMID 36467798, 2022). "Initially, a single mutation was found in these LFL families, p.(R117C), which was also different from the POT1 mutations found in other cancer types." (PMID 35727838, 2022). "Germline POT1 variants with relevance to cancer predisposition were identified because they cosegregate with individuals who present disease." (PMID 35323213, 2022). "In familial melanoma, mutations in POT1 have also been identified and carriers of these mutations are more susceptible to cancer development." (PMID 33599797, 2021). "Numerous deleterious mutations in POT1 have been identified in different human cancers, many of which exist in the DNA-binding domain and disrupt POT1′s binding to 3′-overhangs, promoting telomere elongation and chromosomal instability." (PMID 33599797, 2021). "Regulation of telomeres has been tied to aging and cancer, and mutations of the Pot1 locus in human families are associated with an increase in the incidence of cancer." (PMID 33542458, 2021). "Loss of POT1 leads to accumulation of anaphase bridges and chromosomal fusions which promotes cancer development in mice." (PMID 33599797, 2021). "The data presented here argue that the telomere elongation phenotype associated with the POT1 mutations is sufficient to explain the higher incidence of cancer in these families." (PMID 33258446, 2020). "Sequencing of cancer genomes identified POT1 mutations in several solid tumors and hematological malignancies." (PMID 33122293, 2020). "Although much more needs to be learnt about the role of shelterin proteins in human cancer, some clinical implications of POT1 mutations are beginning to emerge." (PMID 32987645, 2020). "POT1-ΔOB lacks the first OB fold and served as a surrogate for cancer-associated POT1 variants that cannot bind to ssDNA." (PMID 33122293, 2020).
cancer (continued). "Given the importance of POT1 in various cancers, we selected it as our candidate variant for further in silico analyses and functional validation." (PMID 32492864, 2020). "Genotype–phenotype correlation studies, and functional analyses of the biological consequences of cancer-associated POT1 mutations, would advance this area of research." (PMID 32987645, 2020). "To corroborate these results, we used CRISPR/Cas9 to knock-in two cancer-associated mutations at the endogenous POT1 locus." (PMID 33122293, 2020). "Consistent with cancer-associated POT1 mutations causing telomere deprotection, expression of POT1 OB-fold mutations in human cells results in rapid telomere elongation, telomere fragility, and ATR activation." (PMID 33122293, 2020). "Here we aimed to uncover the pathways that enable the proliferation of cells expressing cancer-associated POT1 mutations." (PMID 33122293, 2020). "As telomere maintenance element, telosome (telomere sheltering complex protein) is a complex of 6 proteins (TRF1, TRF2, RAP1, TIN2, TPP1 and POT1) which modulation is one of the ways to promote telomere dysfunction associated to cancer high radiosensitivity." (PMID 30405890, 2018). "Whatever the mechanism, loss of POT1 function promotes end-to-end chromosome fusions and cancer formation, suggesting that POT1 is critically important for preventing the onset of tumour promoting genomic instability." (PMID 28393832, 2017). "To determine if the POT1 cancer mutations maintain telomere length homoeostasis, we carried out southern blot analysis of WT and mutant POT1 transfected HEK293T cells." (PMID 28393830, 2017). "Our findings are compatible with a more extensive spectrum of cancer types associated with POT1 mutation." (PMID 27329137, 2016). "Recently, increasing evidence suggests that telomere maintenance genes, such as TERT, TERC, TERF1, TERF2, TINF2, TERF2IP and POT1 are associated with cancer risk." (PMID 22970196, 2012). "Cdc13 and its putative homologues human CTC1 and POT1 are therefore key to many biological processes directly associated with life extension and cancer prevention and can be viewed as an ideal target for cancer and age related therapies." (PMID 20975208, 2010). "This will have the ability to link with other national registers, for example, cancer registry, to study the age and type of cancers occurring in individuals with POT1 LP/P variants and potentially the clinical utility of the proposed surveillance recommendations." (PMID 40350252, 2025). "Across a diverse range of cancer, including melanoma, cardiac hemangioma, glioma, and colorectal cancer, mutations in the POT1 gene have been implicated in the deregulation of telomere maintenance, manifesting as telomere elongation and enhanced telomere fragility." (PMID 39871386, 2025). "This suggests that the phenotypes observed in human cancers with POT1 mutations may be caused by similar mechanisms." (PMID 39239547, 2024). "We identified 49 POT1 variants reported as associated with cancers other than melanoma." (PMID 38254993, 2024). "Nevertheless, a broader cancer spectrum related to POT1 mutations is described." (PMID 38839987, 2024). "While the impact of POT1 variants on telomere length is the subject of interest in many studies, some authors have shown it as the sole evidence of a variant pathogenicity, due to its correlation with cancer susceptibility." (PMID 38254993, 2024). "Consistently, the cancers that carry mutations in the POT1 OB fold also have long telomeres." (PMID 39483338, 2024). "Furthermore, a proposal of a surveillance protocol related to the cancers associated with POT1 pathogenic variants requires reliable data to avoid an excessive, possibly unjustified, burden for POT1 variant carriers." (PMID 38254993, 2024).